TFEB (transcription factor EB)
Diseases named in the same sentence as TFEB in open-access papers (continued):
Sharing a sentence is not in itself a finding about the gene and the disease.
renal carcinoma (14 papers, 2013 to 2025). A carcinoma arising from the epithelium of the renal parenchyma or the renal pelvis. "TFEB, the somatic translocation of which is implicated in the renal carcinoma, is now implicated in lysosome biogenesis as well as autophagy induction." (PMID 23457579, 2013). "Indeed, dysregulation of members of the microphthalmia family of transcription factors including TFEB have been shown to cause renal carcinomas." (PMID 25069841, 2014). "The molecularly defined renal carcinomas include TFE3-rearranged RCC, TFEB-altered RCC, ELOC-mutated RCC, FH-deficient and SDH-deficient RCC, ALK-rearranged RCC, and SMARCB1-deficient renal medullary carcinomas." (PMID 38235567, 2024). "Studies have further shown that TFEB affects the biological progression of renal cancer by acting on the mTOR pathway and positively correlates with the expression of PD-L1." (PMID 38730456, 2024). "The mouse model of renal carcinoma due to specific renal TFEB overexpression was established, and it was found that highly activated Wnt pathway played an important role in TFEB-induced RCC." (PMID 34490237, 2021). "Whether or not the modulation of p21 also plays a role in the oncogenic activity of TFEB/TFE3-induced renal carcinoma, will be the subject of future studies." (PMID 32397616, 2020). "TFE3-RCC and TFEB-RCC, classified as molecularly defined renal carcinomas in the current WHO classification, may also express HMB45 but are negative for CK7." (PMID 40584698, 2025). "However, using a mouse xenograft generated using a cell line derived from a renal cancer patient with BHD syndrome, we found that silencing of either TFEB or TFE3 was able to rescue the tumorigenic phenotype." (PMID 40189703, 2025). "TFEB/6p21/VEGFA-amplified RCC defined by the 6p21.1 chromosomal region is a rare and gradually recognized RCC subtype that exists independently of TFEB-translocated RCC and has been included in the molecularly defined renal cancer subtypes by the World Health Organization in 2022." (PMID 38730456, 2024).
diabetes (13 papers, 2014 to 2023). "We have suggested that nutrient overload in diabetes causes LD accumulation due to decreased TFEB activation and suppression of autophagy and tested this hypothesis in vitro, using the rat insulinoma β‐cell line INS‐1." (PMID 30710421, 2019). "Our results show that diabetes-induced mTOR activation contributes to TFEB dysfunction and therefore perturbs lysosomal homeostasis by impairing lysosomal biogenesis and clearance in TECs." (PMID 35082964, 2022). "In conclusion, diabetes-induced mTOR activation represses TFEB function, thereby perturbing lysosomal homeostasis through impairing lysosomal biogenesis and clearance in TECs." (PMID 35082964, 2022). "Several studies have reported the therapeutic use of TFEB in fatty liver, diabetes, and cardiac hypertrophy by regulating autophagy." (PMID 33639613, 2021). "For example TFEB gene was not only significant in the T2D and pre-diabetes comparison but also in the healthy and pre-diabetes comparison, with 2.76 and 3.88 times in difference in each pairs of comparisons respectively." (PMID 25559614, 2014). "In the db/db mouse model of diabetes mellitus, high levels of advanced glycation end-products (AGEs) and high glucose suppressed podocyte autophagy by activating mTORC1 and inhibiting the nuclear translocation of transcription factor EB (TFEB)." (PMID 31936109, 2020). "However, TFEB nuclear export is also likely to be deregulated in diabetes where high glucose levels may diminish TFEB residence time in the nucleus thereby impairing the ability of TFEB to fine-tune the response to any intracellular supply-demand imbalance." (PMID 29992949, 2018). "Using real-time PCR, we observed a ∼50% reduction in renal parenchymal TFEB mRNA levels in individuals with diabetic kidney disease in comparison to individuals without diabetes and with normal kidney function." (PMID 29449811, 2018). "Notably, we also found that the “Maturity Onset Diabetes of the Young (MODY)” gene category, which contains genes important for pancreatic β‐cells, including insulin, was among the downregulated enriched gene categories in TFEB‐overexpressing cells." (PMID 37712288, 2023).
ovarian carcinoma (13 papers, 2019 to 2025). A malignant neoplasm originating from the surface ovarian epithelium. "Cisplatin treatment causes the nuclear translocation of TFEB, at least in ovarian cancer cell lines." (PMID 41469472, 2025). "In pancreatic and ovarian cancers, nuclear TFEB activation supports metabolic flexibility and alters inflammasome dynamics, leading to reduced immunogenicity and increased survival under cytotoxic stress." (PMID 40671967, 2025). "Lysosome can initiate calcium signaling through the TRPML-1/TFEB pathway and regulate ovarian cancer cell drug resistance." (PMID 38711526, 2024). "For instance, transcription factor EB (TFEB) promotes CMA in ovarian cancer and PD; NRF2 promotes CMA in oxidative stress; and CMA is negatively regulated by OCT4 and SOX2 in embryonic stem cells." (PMID 37655052, 2023). "Using ChIP and functional Luciferase Assays, we confirmed that TFEB is able to directly transactivate ATP7B in the presence of Pt in resistant ovarian cancer cells." (PMID 35053335, 2022). "Our own findings suggest that inhibitor of TFEB nuclear translocation increases cisplatin toxicity in another ovarian cancer cell line A2780-CP20, whose resistance to Pt involves elevated ATP7B expression." (PMID 35053335, 2022). "In ovarian cancer, hypoxia significantly increases the release of TEXs by reducing endolysosomal fusion and increasing the expression of transcription factor EB (TFEB) that can favor the lysosome docking." (PMID 31438991, 2019). "In addition, in ovarian cancer cells, TFEB is involved in cisplatin resistance by regulating the tumor microenvironment." (PMID 37445831, 2023). "Also, ATP7B, a lysosomal protein that is induced by TFEB and mediates the cisplatin lysosomal sequestration in resistant ovarian cancer cells, was down-regulated in TFEB-silenced cells compared to wild-type cells, excluding that it was involved in cisplatin resistance upon TFEB silencing." (PMID 39107857, 2024). "Cisplatin induces TFEB nuclear translocation, upregulates downstream PD-L1 and PD-L2, and forms an immune-suppressive cancer microenvironment; this mediates cancer immune escape and drug resistance, and can be used to target TFEB inhibition to increase ovarian cancer cell cisplatin sensitivity." (PMID 38711526, 2024). "Finally, we tested whether this TFEB suppression strategy is effective in another ovarian cancer A2780-CP20 cell line, whose resistance to cisplatin relies on ATP7B in a significant manner." (PMID 35053335, 2022). "The suppression of TFEB inhibits ATP7B expression and sensitizes initially resistant ovarian cancer cells to cisplatin." (PMID 37445831, 2023). "Using resistant ovarian cancer IGROV-CP20 cells, we found that TFEB directly binds to the predicted coordinated lysosomal expression and regulation (CLEAR) sites in the proximal promoter and first intron region of ATP7B upon Pt exposure." (PMID 35053335, 2022). "Besides, NEO212 was capable to down-regulate a series of lysosome related gene expression via hindering the nuclear translocation of TFEB, and in turn block the autophagic flux, implying NEO212 might as a promising therapeutic agent against ovarian cancer." (PMID 31174569, 2019). "NEO212 inhibited TFEB translocation, and impaired the lysosomal function, implying NEO212 might avoid from autophagy mediated chemo-resistance, thus proposing NEO212 as a potential therapeutic candidate for ovarian cancer." (PMID 31174569, 2019).
renal tumors (13 papers, 2010 to 2024). "A gene fusion involving the transcription factor EB (TFEB) 6p21 locus was first described in 2001 in a pediatric renal neoplasm." (PMID 37999735, 2024). "Fourth, mutations in FLCN, which similarly disrupt the FLCN/FNIP GAP complex, result in renal tumors, which can be abrogated by the simultaneous inactivation of TFEB." (PMID 37627070, 2023). "Here we show, using murine disease‐relevant models as well as BHD‐associated renal tumors, that both TFEB and TFE3 play important roles not only in the kidney cystic phenotype but also in human renal tumor formation." (PMID 36987696, 2023). "It is worth noting that amplification of TFEB gene can rarely be found in various renal tumors, most of which are usually unclassified RCCs or translocation-like RCCs." (PMID 31905821, 2019). "The mechanisms leading from TFE3/TFEB gene overexpression to kidney tumor development remain largely uncharacterized, thus the need for modeling these diseases in experimental animal systems for the identification of effective targeted therapies." (PMID 27668431, 2016). "Furthermore, the high severity of the renal cystic phenotype of kidney‐specific Flcn KO mice leads to early lethality, before the development of kidney tumors, thus hampering the evaluation of the role of TFEB/TFE3 in kidney tumorigenesis." (PMID 36987696, 2023). "This may be explained by either their early death due to renal failure that occurs before renal neoplasia can develop or by differences in the degree of mTOR hyperactivation between TFEB overexpressing mice and Six2Cre+Tfap2bfl/fl mice." (PMID 35468900, 2022). "In addition, Alpha-TFEB gene fusions were found in primary renal tumors, which could result in the expression of intact TFEB proteins through strong Alpha gene promoter activity." (PMID 21209915, 2010). "As previously stated, TFEB-altered RCC has been included in the MiTF-translocated carcinoma family and TFEB-overexpressing renal tumors were initially identified in pediatric patients." (PMID 37367052, 2023). "Remarkably, the analysis of BHD patient‐derived tumor samples revealed increased activation of TFEB/TFE3‐mediated transcriptional program and silencing either of the two genes rescued tumorigenesis in human BHD renal tumor cell line‐derived xenografts (CDXs)." (PMID 36987696, 2023). "Among these renal tumors, ten cases meet the morphologic, immunohistochemical and FISH characterization for TFEB rearranged RCC." (PMID 36830782, 2023). "Renal tumors with TFE3, TFEB, and MiTF rearrangements are “classic” translocation-associated RCCs, being diagnosed based on a combination of morphologic, immunohistochemical, and molecular genetic analyses." (PMID 31905821, 2019). "Additionally, TSC1/2 alterations have been described in novel and emerging renal tumor subtypes including ESC-RCC, eosinophilic vacuolated tumors, TFEB-altered RCC, low-grade oncocytic tumors (LOT), and eosinophilic vacuolated tumors (EVT)." (PMID 37999735, 2024). "Whereas mice that overexpress TFEB in the kidney develop renal papillary carcinomas by about 5 months of age, we did not observe renal neoplasia in the examined 1-2-months-old Six2Cre+Tfap2bfl/fl mice." (PMID 35468900, 2022).
Insulin resistance (12 papers, 2017 to 2025). Increased resistance towards insulin, that is, diminished effectiveness of insulin in reducing blood glucose levels. "The BMs suggest that the development of insulin resistance is linked to the activity of the transcription factor TFEB." (PMID 39429779, 2024). "Together, these data demonstrate that TFEB deficiency in skeletal muscle results in peripheral insulin resistance-reduced glucose uptake and decreased glycogen content." (PMID 28011087, 2017). "Hypothetically, in GD placentas, the decrease in mTOR caused by insulin resistance may lead to dephosphorylation of TFEB and its translocation to the nucleus." (PMID 41226334, 2025). "The Boolean model suggests that the dysregulation of TFEB and its regulated genes plays an important role in insulin resistance and controlling mitochondrial function in PD." (PMID 39429779, 2024). "We previously demonstrated that TFEB promotes lipid catabolism in the liver and protects against diet-induced weight gain and insulin resistance." (PMID 28011087, 2017). "Interestingly, the study found that overexpression of TFEB improve insulin resistance, furthermore they also showed that autophagy flux was restored when TFEB was overexpressed, even in the presence of palmitic acid." (PMID 41439967, 2025). "Similarly, the adenovirus-mediated overexpression of transcription factor EB, a master regulator of lysosomal biogenesis and autophagy, ameliorates insulin resistance in mice fed a HFD or in ob/ob mice." (PMID 29540751, 2018). "However, high levels of the inactive form of TFEB suggest a decrease in 14-3-3 proteins, which may increase the aggregation of alpha-synuclein and impair cellular processes, leading to insulin resistance." (PMID 39429779, 2024). "Consistent with the presence of insulin resistance, we detected decreased AKT phosphorylation in TFEB KO muscles." (PMID 28011087, 2017).
metabolic syndrome (12 papers, 2017 to 2025). A cluster of metabolic risk factors for CARDIOVASCULAR DISEASES and TYPE 2 DIABETES MELLITUS. "Given that nuclear TFEB localization declines with age or decreased renal function, TFEB deficiency in PTECs is considered to be one of the reasons for dyslipidemia in patients with CKD." (PMID 39699959, 2024). "Independent studies have shown that activation of TFEB can provide protection from the effects of the metabolic syndrome by improving the capacity of the cell to upregulate autophagy." (PMID 34338148, 2022). "Given the critical role of TFEB in hepatic lipid metabolism, accumulating evidence has shown that TFEB can be a promising therapeutic target for metabolic syndrome." (PMID 35625599, 2022). "In animals receiving a high-fat diet, overexpression of TFEB prevented the development of obesity and improved the metabolic syndrome phenotype by reducing abnormal levels of circulating triglycerides, cholesterol, glucose and insulin." (PMID 32854299, 2020). "The newly discovered small-molecule TFEB agonists will facilitate studies focused on new TFEB biology and will promote viable pharmacological strategies to tackle metabolic syndromes, ageing and age-related diseases." (PMID 29273768, 2017). "Increasing TFEB activity is beneficial to diseases related to metabolic syndrome." (PMID 35625599, 2022). "High TFEB activity was also able to revert the metabolic syndrome when it was already present." (PMID 32854299, 2020). "TFEB activation induced by digoxin engages lipid catabolism and ameliorates metabolic syndromes." (PMID 33292395, 2020). "Studies have shown that dyslipidemia, particularly via oxidized low-density lipoprotein (LDL), disrupts normal autophagy by inhibiting the activity of transcription factor EB (TFEB), resulting in decreased autophagic flux and increased necroptosis in chondrocytes." (PMID 39457494, 2024).
viral infection (12 papers, 2020 to 2026). "CVB3 uses proteinase 3C to proteolyze TFEB (transcription factor EB), a master regulator of autophagy and lysosome biogenesis, into a loss-of-function cleavage fragment to disrupt host lysosomal function and enhance viral infection." (PMID 41277866, 2026). "CVB3 proteinase 3C disrupts host lysosomal function via proteolysing transcription factor EB (TFEB), a master regulator of autophagy and lysosome biogenesis, into a lower-molecular-mass, loss-of-function cleavage fragment, thereby enhancing viral infection." (PMID 41277866, 2026). "Mechanistically, we found that viral infection modulated TFEB expression in a growth phase and time‐dependent manner." (PMID 41204829, 2026). "To further validate the impacts of DCAF7 on TFEB protein and viral infection, we reexpressed DCAF7 in DCAF7 KO cells." (PMID 40465712, 2025). "Several other recent studies have demonstrated the complexity of TFEB-driven host response to viral infection in various model systems." (PMID 40465712, 2025). "We observed that PAK2 activation is a critical priming step for TFEB degradation as this kinase is activated by viral infection, generating a phospho-degron required for subsequent DCAF7 recognition (see the model in fig." (PMID 40465712, 2025). "Here, we describe a previously unidentified aspect of coronaviral infection, whereby the master transcriptional activator of lysosomal homeostasis—TFEB—is targeted for proteasomal-mediated degradation upon viral infection." (PMID 40465712, 2025). "Overall, our findings reveal a previously unrecognized mechanism by which TFEB promotes virus infections—inhibition of cell-intrinsic defenses restricting virus entry." (PMID 33880473, 2022). "Overall, our findings reveal what to our knowledge is a previously unrecognized mechanism by which TFEB promotes virus infections via inhibition of cell-intrinsic defenses restricting virus entry." (PMID 36264642, 2022). "Here, we describe a novel aspect of coronaviral infection, whereby the master transcriptional regulator of lysosome biogenesis - TFEB - is targeted for proteasomal-mediated degradation upon viral infection." (PMID 34013250, 2021). "We hypothesized that viral infection might alter the phosphorylation of TFEB, marking the protein for ubiquitination." (PMID 40465712, 2025). "Our data demonstrate that viral infection induces the proteasomal degradation of TFEB." (PMID 40465712, 2025). "The mammalian Target of Rapamycin Complex 1 (mTORC1) signaling pathway was identified as the key regulator of viral infection; inhibiting this pathway activated transcription factor EB, which promoted the release of coxsackievirus virions through extracellular vesicles." (PMID 40577348, 2025). "As proteasomal-dependent protein turnover is recognized as a major cellular mechanism regulating transcription factor activity, we questioned whether TFEB turnover was modulated by viral infection." (PMID 40465712, 2025). "Furthermore, TFEB protein was substantially preserved during viral infection when cotreated with inhibitors of ubiquitin-proteasome system (UPS), including carfilzomib (CFZ; proteasome inhibitor), TAK-243 (ubiquitin E1 inhibitor), and MLN4924 (NEDD8 E1 inhibitor)." (PMID 40465712, 2025). "Transcription factor EB (TFEB), which is targeted for proteolytic processing to disrupt lysosomal function and enhance viral infection, has been identified as a new target of CVB3 proteinase 3C." (PMID 36653801, 2023). "In particular, viral infection triggers marked PAK2 activation, which in turn, phosphorylates and primes TFEB for ubiquitin-mediated protein degradation." (PMID 34013250, 2021). "In agreement with our findings, TFEB activation following viral infection occurred without a noticeable change in mTORC1 activity." (PMID 40465712, 2025).